S100A2 (S100 calcium binding protein A2)
Diseases named in the same sentence as S100A2 in open-access papers (continued):
Sharing a sentence is not in itself a finding about the gene and the disease.
cancer (continued). "S100A2 is a well-studied S100s member in cancer, which is closely related to the occurrence of various human tumorigenesis." (PMID 34804125, 2021). "Our data show that S100A2 expression is silenced in many cancer cell lines and can be restored by 5-Aza-dC treatment." (PMID 26097874, 2015). "S100A2 is a member of the S100 gene family, where S100 proteins are Ca2+ binding proteins with broad implications in cancer." (PMID 26474385, 2015). "On the other hand, calcium binding protein S100A2 functioning as tumor metastasis protein has been reported to be methylated in 75% cancer tissues and in 100% BPH tissues." (PMID 25938433, 2015). "For example, S100A4, S100A6, S100A7 and S100B play oncogenic roles in cancer development, whereasS100B, S100A2, and S100A11 are believed as TSGs." (PMID 23894350, 2013). "While abnormal expression of many S100A proteins were found in cancer cells, changes of S100A2 and S100A10 expression were reported in various SCC of the oral cavity, esophagus, the larynx, kidney, and the thyroid." (PMID 21897749, 2011). "While overexpression of S100A2 led to increased migratory capability of cancer cells." (PMID 40092486, 2025). "It is also possible that S100A2’s function as a transcriptional cofactor is more prominent in ccRCC due to the differential expression or activity of interacting proteins like HNF1A in this cancer type." (PMID 40011447, 2025). "The dual nature (promotion or inhibition) of S100A2 in different cancer types shows the complex involvement of its tumorigenesis, but its effect in ccRCC remains unclear." (PMID 40011447, 2025). "The dual nature of S100A2 in different cancer types underscores the complexity of its involvement in tumorigenesis, suggesting that its function may be context-dependent." (PMID 40011447, 2025). "Notably, expression of S100A2 was seen to be significantly different across different cancer types, with increased expression in most cancers, but decreased in a few cancer types (BRCA, KICH, and KIRC)." (PMID 38684596, 2024). "It has been reported that S100A2 is involved in the pathogenesis of many cancers." (PMID 39739972, 2024). "The altered expression of S100A2 is a potential marker for cancer diagnosis and prognosis." (PMID 37758734, 2023). "Furthermore, we describe in detail the influence of S100A2 on malignant tumors and inflammatory diseases." (PMID 35885660, 2022). "The role of S100A2 in benign tumors is also unknown; however, its expression can also be used as a marker to distinguish it from other benign or malignant tumors." (PMID 35885660, 2022). "S100A2 seems to have both carcinogenic and anticancer effects in cancer." (PMID 34804125, 2021). "At the single-cell level, we defined S100A2 as a potential biomarker for cancer cells in PASC." (PMID 34326696, 2021). "We found that S100A2 is a potential biomarker for cancer cells." (PMID 34326696, 2021). "It was found that S100A2 was mainly expressed by cancer cells in PC tissues." (PMID 34887861, 2021). "While few studies describing genetic alterations in S100A2 gene in cancer exist, epigenetic mechanisms could also account for disturbance of S100A2 function." (PMID 26097874, 2015). "We correlated DNA hypermethylation of S100A2 in cancer samples with clinical and histopathological variables to determine whether these alterations were associated with any particular phenotype." (PMID 26097874, 2015). "However, whether S100A2 is the central player downstream of N4BP1 in cancer cells remains to be explored." (PMID 41513619, 2026).
cancer (continued). "Similarly, most of the genes specifically expressed in normal epithelial cells were the pancreatic epithelial cell functional genes, and the primary cancer cells expressed the genes that were highly associated with the development of PDAC, including TFFs, S100A2, PSCA, CST6 and many others." (PMID 36307773, 2022). "Additionally, aberrant S100A2 expression in cancer has been demonstrated in many studies." (PMID 26097874, 2015). "Furthermore, this study supports the concept that enhanced expression of S100A2 may be a promising strategy in developing novel cancer therapeutic drugs." (PMID 25874882, 2015). "In this study, the downregulation of S100A2 inhibited PDAC cell metastasis, but its overexpression enhanced cancer metastasis." (PMID 37758734, 2023). "COL17A1, KRT15, KRT17, S100A2, SFN, which have been shown to assume oncogenic roles in various cancers, were among the highly changed genes and positively correlated with p63 expression." (PMID 38012140, 2023). "S100A2, TGFA, MET, PCNA, SCD, GDF15, and PAI1 act as oncogenes by promoting cancer metastasis or proliferation 24-30." (PMID 34131400, 2021). "The data showed that S100A4, S100A14 and S100A16 were significantly higher in PDAC tissues compared with their counterparts, but the protein level of S100A2, S100A6 and S100A10 were similar between cancer tissues and their counterparts." (PMID 34530774, 2021). "The expression of S100A2 is induced by transforming growth factor-β (TGF-β) in DICS, which is a potent inducer of EMT and cancer progression." (PMID 32053966, 2020). "Among these genes, only expression levels of GJB2, S100A2, SPOCK2 and TGM1 were significantly upregulated in cancer samples and their high expression indicated poor prognosis (OS or RFS)." (PMID 31794425, 2019). "In basal‐like cancer, there was a positive correlation of KLK6 and S100A11 and S100A2, in accordance with our findings." (PMID 30980596, 2019). "For example, the over-expression of S100A2, S100A3, S100A6, S100A8/A9, S100A11 and S100A14 have been documented in several cancer types." (PMID 30018736, 2018). "For example, over-expression of S100A2, S100A3, S100A6, S100A8/A9, and S100A11 is related to several types of cancer, whereas other types of cancer are characterized by the under-expression of these same proteins." (PMID 25988147, 2014). "Most noticeably, abnormal expression of many S100 proteins, such as S100A2, S100A4, S100A6, S100A8, S100A9, S100A10, and S100A11 is found in numerous cancers." (PMID 21897749, 2011). "The identification of many well-defined cancer gene markers (representing oncogenes), such as EGFR, osteopontin (SPP1), ERBB3, MALAT1, S100A2, S100A6, ABCC3 and ELN3, as highly discriminative genes by the ECD is quite encouraging." (PMID 22369099, 2011). "We performed a comparative analysis of S100A2 staining patterns in cancer and non-cancerous tissues across 13 different tissue types." (PMID 38684596, 2024). "The higher levels of S100A2, S100A11, and S100A14 transcript in the eight cancer cell lines than in the HPNE control cell line suggest that these three S100s might modulate the behavior of the cancer cells." (PMID 37627239, 2023). "In addition, we found that macrophage subpopulations (clusters 1, 5, 7, 8, and 9) from cancer tissues expressed a certain number of immunosuppressive genes, such as VEGFA, MMP14, MMP19, S100A2, APOE, HMOX1, SLAMF7, SIRPα, LAG3 and IL18." (PMID 36158683, 2022). "Interestingly, the multifunctional, Ca++-binding S100A2 gene was one of few genes conserved in all 3 cohorts and S100P was conserved in the NEK and KRAS-mut cancers." (PMID 36612014, 2022). "Similarly, S100A2, KRT14, KRT17, and KRT6A were overwhelmingly expressed in cancer cells and their expression values were significantly higher than the other cells (log10FC > 3 and P < 0.001)." (PMID 34326696, 2021).
cancer (continued). "Hypermethylation of the S100A2 promoter was found in the eight cancer cell lines which were previously found not to express S100A2 (011, 012, 022, 028, 5637, HT1376, J82, and SCaBER)." (PMID 26097874, 2015). "The S100A2 gene is located within the epidermal differentiation complex (EDC) on chromosome 1q21 and is in a region that is frequently rearranged in many types of human cancer, including NSCLC." (PMID 15467767, 2004). "The role of S100A2, recognized as a bad prognosis biomarker in cancer, is not known in the eye." (PMID 34502527, 2021). "In our study, gene expression analyses show that S100A2, S100A11, and S100P expression levels in CRC tissues are significantly higher than those in noncancerous tissues, and S100A3 and S100A9 mRNAs are highly expressed in cancer tissues compared with normal tissue controls." (PMID 33294444, 2020).
adenocarcinoma (7 papers, 2004 to 2024). A common cancer characterized by the presence of malignant glandular cells. "S100A2 is commonly considered to be a sign of PC progression due to its significance in differentiation of adenocarcinoma." (PMID 34527585, 2021). "Interestingly, although many adenocarcinomas (10 out of 24) did express S100A2, we found that expression correlated more closely with a squamous histology (16 out of 19)." (PMID 15467767, 2004). "S100A2/maspin-negative adenocarcinomas may similarly arise from such multipotent progenitors, in which case they would represent a clonal lesion more closely associated with the expression pattern of a differentiated peripheral airway cell or else they may actually arise from such a cell." (PMID 15467767, 2004).
infection (2 papers, 2010 to 2024). The state of being infected such as from the introduction of a foreign agent such as serum, vaccine, antigenic substance or organism. "It appears as if the presence of S100A2 is important for optimal RXRγ expression, but this is most likely not a direct interaction as measurable and at least partially functional RXRγ (as evidenced by response to LGD1069) was seen after shS100A2 infection." (PMID 19859558, 2010).
benign tumor (1 paper, 2022). "Several benign tumors are known to be associated with the expression of S100A2." (PMID 35885660, 2022). "Craniopharyngioma is a benign tumor that exhibits positive S100A2 expression." (PMID 35885660, 2022).
kidney diseases (1 paper, 2024). "Importantly, compared to the low fibrosis groups, the high fibrosis groups of several kidney diseases exhibited significantly elevated expression of S100A2 in kidney tissues, suggesting the potential involvement of S100A2 in fibrosis." (PMID 39382800, 2024).
S100A2 also shares sentences with these, for which no sentence is quoted: esophageal squamous cell carcinoma (3 papers); benign prostate hyperplasia (2); lymph node metastasis (2); osteosarcoma (2); alcohol abuse (1); alopecia areata (1); anaplastic carcinoma (1); astrocytoma (1); bacterial infection (1); Barrett adenocarcinoma (1); Calicivirus Infection (1); clear cell renal cell carcinoma (1); diabetic nephropathy (1); eczema (1); endometrioid ovarian cancer (1); epitheliomas (1); eye inflammation (1); follicular carcinoma (1); gallbladder cancer (1); gastric tumor (1); gastritis (1); glaucoma (1); hypertensive nephropathy (1); IgA nephropathy (1); invasive ductal carcinoma (1); Kawasaki disease (1); keratoconus (1); large cell carcinoma (1); low grade glioma (1); nasal polyps (1).
A further 19 diseases each share a sentence with S100A2 in 1 paper.